CDCP1 (CUB domain containing protein 1)
Diseases named in the same sentence as CDCP1 in open-access papers (continued):
Sharing a sentence is not in itself a finding about the gene and the disease.
breast carcinoma (continued). "The precise role of PTP1B in the regulation of CDCP1 in breast cancer progression remains to be determined; nevertheless, these results provide proof-of-principle that the substrate-trapping BirA∗-PTP1B D181A mutant is sufficiently sensitive and robust to identify novel PTP substrates." (PMID 37080392, 2023). "TA reduced CDCP1 cleavage in MDA-MB-231 breast cancer cells." (PMID 35095503, 2021). "Targeting CDCP1 using function blocking monoclonal antibodies inhibits vascular metastasis of prostate cancer 26, intraperitoneal progression of ovarian cancer 13,27 and subcutaneous growth of lung and breast cancer 28 in mouse xenograft models." (PMID 32226543, 2020). "Further supporting that CDCP1 is important in breast cancer resistance to trastuzumab, a more recent study demonstrated that CDCP1 and HER2 are co-overexpressed in 12% of primary and 30% of metastatic breast tumors, and that co-expression correlates with poorest disease free and overall survival." (PMID 26973855, 2016). "Importantly, both in vitro and in vivo the CDCP1 enhanced Src-HER2 interaction drove breast cancer trastuzumab resistance, with dual targeting of HER2 and Src able to overcome resistance in a mouse model." (PMID 26973855, 2016). "The gain in CDCP1 copy number in 38% of CDCP1-positive TNBC cases by FISH and the evidence that tumors with a high number of cells that express CDCP1 also bear many cells with alterations in CDCP1 support that a genetic gain in CDCP1 in this breast cancer subtype is involved in CDCP1 expression." (PMID 27626701, 2016). "It has been proposed that CDCP1 interacts with SDC1 in a human breast cancer cell line, MDA-468." (PMID 25275584, 2014). "It is interesting to note that of the nine 1.2 μM MMC(T60)-responsive genes, GPM6A and CDCP1 are tagged with single nucleotide polymorphisms that are shown by CGEMS to be associated with breast cancer risk (P<0.05) (data not shown)." (PMID 20174566, 2010). "Several studies have shown that miRNA-328 and CDCP1 (CUB-domain containing protein 1) can promote the occurrence and metastasis of breast cancer by regulating fatty acid β-oxidation (FAO)." (PMID 38655619, 2024). "In metastatic human breast cancer cell line MDA-MB-231, which highly expresses the HGF receptor MET and CDCP1, we show that CDCP1 knockdown attenuated HGF-induced MET activation, followed by suppression of lamellipodia formation and cell migration/invasion." (PMID 35085554, 2022). "CDCP1 is overexpressed and its ectodomain is cleaved by extracellular proteases in RAS-driven cancers, such as breast cancer." (PMID 35885460, 2022). "SRC is broadly overexpressed in luminal breast cancer and can crosstalk with HER2 when facilitated by other molecules such as CDCP1." (PMID 32771039, 2020). "EPSTI1 for breast cancer, AR for prostate cancer, GRAP for oral squamous cell carcinoma, CDCP1 and PLAGL2 for ovarian cancer were the only five direct targets identified for miR‐654‐5p thus far." (PMID 33135351, 2020). "CDCP1 expression regulation, upon PDGFRβ/ERK1/2 pathway activation, was investigated also in non-breast cancer cells." (PMID 29792166, 2018). "Ternary complex formation among CDCP1, EGFR, and Src is paralleled by disruption of cell-cell and cell-substratum adhesion in human breast carcinoma cells, coincident with relocalization of E-cadherin from cell-cell junctions to cytoplasmic vesicles." (PMID 27495374, 2016). "CDCP1 and EGFR cooperate to induce detachment of breast cancer cells from the substratum and to disrupt adherens junctions." (PMID 27495374, 2016). "Breast cancer cell lines were engineered to stably express EGFR, CDCP1 or phosphorylation site mutants of CDCP1." (PMID 27495374, 2016). "We demonstrated that CDCP1 promoted HGF-induced migration and invasion of breast cancer cells." (PMID 35085554, 2022).
breast carcinoma (continued). "Additionally, FBXL14 targets and degrades CUB domain-containing protein 1 (CDCP1) to reduce its stability and prevent CDCP1 target genes involved in breast cancer metastasis." (PMID 32226545, 2020). "CDCP1, not previously known to be either a PTP1B interactor or substrate, is a tyrosine-phosphorylated transmembrane glycoprotein that regulates protein trafficking and has been implicated in breast cancer tumorigenesis, metastasis, and cell migration." (PMID 37080392, 2023). "We then examined whether CDCP1 affects the ability of TNBC cells to form vascular-like structures in vitro—another feature of aggressiveness that we recently reported in TNBC cell lines and in human TNBC specimens —compared with other breast cancer subtypes." (PMID 27626701, 2016). "To further confirm the role of CDCP1 in HGF signaling, we subsequently employed a low invasive/nonmetastatic breast cancer cell line T47D, which had no significant expression of either protein and no invasive activity." (PMID 35085554, 2022). "CDCP1, a transmembrane protein with tumor pro-metastatic activity, was recently identified as a prognostic marker in TNBC, the most aggressive breast cancer subtype still lacking an effective molecular targeted therapy." (PMID 29792166, 2018). "In contrast, in the low invasive/nonmetastatic breast cancer cell line T47D, which had no detectable MET and CDCP1 expression, ectopic MET expression stimulated the HGF-dependent activation of invasive activity, and concomitant CDCP1 expression activated SRC and further promoted invasive activity." (PMID 35085554, 2022).
prostate carcinoma (24 papers, 2011 to 2025). A carcinoma that arises from epithelial cells of the prostate gland. "Of note, elevated CDCP1 expression has been associated with the metastatic progression of pancreatic, breast and prostate cancers as well as of melanoma 26, 28-31." (PMID 36276654, 2022). "Due to the low abundance of CDCP1, we pooled and concentrated samples from high-risk and low-risk prostate cancer patients." (PMID 26497208, 2015). "We propose that dysregulated processing and expression of extracellular CDCP1 reflect the tumor microenvironment and a full structural characterizationis warranted to determine if circulating CDCP1 can provide a diagnostic/prognostic tool for management of prostate cancer." (PMID 26497208, 2015). "Some cancers, like prostate cancer, secrete EVs with CUB-domain containing protein 1 (CDCP1), a transmembrane protein inducer of osteoclastogenesis that has been shown to have an amplified effect in the presence of RANKL." (PMID 40722712, 2025). "The MR results using the IVW method showed two factors that were protective against prostate cancer: CUB domain-containing protein 1 (OR: 0.95, 95% CI: 0.91–0.99, P = 0.015) and Interleukin-10 receptor subunit beta (OR: 0.95, 95% CI: 0.91–0.98, P = 0.005)." (PMID 38874503, 2024). "For prostate cancer, CUB domain-containing protein 1 and Interleukin-10 receptor subunit beta were found to be protective, while Glial cell line-derived neurotrophic factor and SIR2-like protein 2 were identified as risk factors." (PMID 38874503, 2024). "Antibody A406 was also effective at delivering 89Zr for detection and 177Lu for radio-ligand therapy of CDCP1 expressing prostate cancer xenografts in mice." (PMID 36276654, 2022). "Cytotoxicity of MMAE-labelled ch10D7 against kidney, colorectal, lung, ovarian, pancreatic and prostate cancer cells in vitro, correlates with the level of CDCP1 on the plasma membrane." (PMID 36276654, 2022). "With complementary models, the authors demonstrated that CDCP1 is a powerful driver of prostate cancer progression, opening new potential therapeutic strategies." (PMID 34572036, 2021). "Antibody 10D7 effectively blocks CDCP1 function inhibiting its roles in mouse models of vascular metastasis of prostate cancer 26 and intraperitoneal progression of ovarian cancer 13,27." (PMID 32226543, 2020). "Consistent with a role in resistance to therapy, doxorubicin-induced apoptosis of prostate cancer cells in vitro is disrupted by CDCP1, with antibody blockade of CDCP1 restoring chemosensitivity." (PMID 26973855, 2016). "These and other phenotypic changes in CDCP1 are faithfully conserved in extracellular vesicles derived from prostate cancer cells." (PMID 26497208, 2015). "In summary, although localization of CDCP1 is altered, the overall expression in prostate cancer tissues as performed on FFPE material is heterogeneous making CDCP1 a poor candidate as a tissue based biomarker." (PMID 26497208, 2015). "Given that proteolytic cleavage of the ectodomain correlates with outside-in oncogenic signaling, we characterized glycosylation in the context of cellular processing and expression of CDCP1 in prostate cancer." (PMID 26497208, 2015). "We examined a tissue microarray containing 100 human primary prostate cancer specimens for expression of CDCP1 in tumors compared with adjacent normal epithelial tissue." (PMID 26497208, 2015). "Previous experimental data for CDCP1 in prostate cancer has been restricted to the study of PC3 and DU145 cancer models." (PMID 26497208, 2015). "We examined the expression of CDCP1 in frozen human prostate cancer tissues via immunofluorescence microscopy." (PMID 26497208, 2015). "Restoration of KAI1 expression in PC3 human prostate carcinoma cells blocked Src activation through negative regulation of CDCP1." (PMID 22390300, 2012). "Significantly, inhibiting CDCP1 with an anti-CDCP1 antibody was shown to block tumor growth and metastasis in prostate cancer." (PMID 22390300, 2012).
prostate carcinoma (continued). "CUB domain-containing protein 1 (CDCP1) is widely expressed in tumors, including prostate cancer, and it is recognized by the chimaeric mAb 25A11 (ch25A11)." (PMID 22069735, 2011). "CDCP1 has been identified in prostate cancer-EVs, indicating the presence of this cell surface protein on EVs may be a biomarker for cancer." (PMID 35982068, 2022). "We next assessed the level of cell surface CDCP1 in 49 cell lines from a diverse range of adenocarcinomas, including seven from kidney, nine from lung, four from colorectal, 20 from ovarian and two from prostate cancer and seven from PDAC." (PMID 36276654, 2022). "CDCP1 is also present in extracellular vesicles isolated from prostate cancer cell lines." (PMID 26497208, 2015). "Given current affinity reagents, CDCP1 expression in FFPE tissues does not appear to provide diagnostic value for prostate cancer." (PMID 26497208, 2015). "This is the first report of circulating CDCP1 detected in prostate cancer patients." (PMID 26497208, 2015). "Hence, KAI1 acts through down-regulation of CDCP1 protein to inhibit Src activation in PC3 prostate cancer cells." (PMID 22390300, 2012). "Therefore, we investigated another target of KAI1 present in prostate cancer that interferes with Src signaling: CDCP1." (PMID 22390300, 2012). "Clinically, this is important because CDCP1 expression is often elevated in primary cancers and prognostic of poor outcome and survival; however, recent evidence indicates its expression actually decreases within metastatic prostate cancer lesions (B. Knudsen, personal communication)." (PMID 25730905, 2015). "A variety of other surface targets are currently under evaluation in prostate cancer, including bombesin, prostate stem cell antigen (PSCA), CUB-domain-containing protein 1 (CDCP-1), CD46, human kallikrein 2 (hK2), delta-like ligand 3 (DLL3), and TROP-2." (PMID 37259457, 2023). "While the ATF has previously been shown to be shed from the surface of prostate cancer cells in vitro and to be present in the serum of colorectal cancer patients 17, this study for the first time demonstrated that this fragment of CDCP1 could be retained on the cell surface." (PMID 32226543, 2020). "Collectively, these observations demonstrate that the metastasis-suppressive activity of KAI1 is highly relevant to the down-regulation of CDCP1 and suppression of HIF-1α expression in prostate cancer." (PMID 22390300, 2012). "Another example related to prostate cancer is a recent study where the authors showed in mice that CDPC1 (CUB domain-containing protein 1), a transmembrane protein that is a substrate for SRC family kinase, can drive prostate cancer progression via activation of the MAPK signaling pathway." (PMID 34572036, 2021). "In addition, we evaluated the differential glycosylation and expression of CDCP1 between aggressive and non-aggressive prostate cancer cells and human tissues." (PMID 26497208, 2015). "In our hands, the only cell line that showed an efficient cleavage of CDCP1 is the PC3 prostate cancer cell line and we observed an equivalent binding of SHP2 to the 130kDa or to the 70 kDa phosphorylated forms of CDCP1 (not shown)." (PMID 25876044, 2015).
bladder cancer (19 papers, 2019 to 2025). "In bladder cancer cells, YTHDF1 preferentially binds to the m6A mRNA of oncogene CUB domain containing protein 1 (CDCP1) to promote its translation, leading to the malignant transformation of urinary tract epithelium and occurrence of bladder cancer." (PMID 33692959, 2021). "The methylation level of oncogene CDCP1 in the 3’ UTR significantly increased in bladder cancer cells." (PMID 33692959, 2021). "We previously demonstrated an oncogenic role of m 6 A-modified CUB domain containing protein 1 (CDCP1) in bladder cancer (BC) progression." (PMID 33267838, 2020). "METTL3 and CDCP1 are both upregulated in bladder cancer patient samples and related to bladder cancer progression." (PMID 32765970, 2020). "The increased m6A modification and translation of oncogene CDCP1 in the transformed uroepithelial cells indicates the potential role of METTL3/m6A/CDCP1 axis in bladder cancer oncogenesis." (PMID 30796352, 2019). "In bladder cancer, METTL3 and oncogene CDCP1 are up-regulated, correlating with bladder cancer progression status." (PMID 31801551, 2019). "We further compared the CDCP1 mRNA and protein levels in the chemical-transformed cells and other bladder cancer cells." (PMID 30796352, 2019). "The upregulated METTL3 and CDCP1 in bladder cancers and the correlation between high METTL3/CDCP1 expressions with advanced bladder cancer stages suggested the important function of METTL3-m6A-CDCP1 axis in regulation of bladder cancers." (PMID 30796352, 2019). "Taken together, METTL3 and CDCP1 expression are upregulated in human bladder cancer samples and the expression of METTL3 and CDCP1 are associated with bladder cancer progression." (PMID 30796352, 2019). "In a chemically induced bladder cancer model of normal human uroepithelial SV-HUC-1 cells and prostate epithelial RWPE-1 cells, METTL3 can upregulate CUB domain-containing protein 1 (CDCP1) in bladder cancer tissues using both methylation-dependent and methylation-independent mechanisms of METTL3." (PMID 36008936, 2022). "Three other pathways are also associated with METTL3 upregulation in bladder cancer, including the METTL3 -CDCP1 (CUB Domain Containing Protein 1), METTL3-ITGA6(Integrin Subunit Alpha 6), and METTL3/YTHDF2-SETD7/KLF4(SET Domain Containing Lysine Methyltransferase 7/ Kruppel Like Factor 4) m6A axes." (PMID 32765970, 2020). "Moreover, the expression levels of METTL3 and CDCP1 are further elevated in the muscle-invasive bladder cancer samples." (PMID 30796352, 2019). "Another previous study corroborated our findings, which revealed that both METTL3 and CDCP1 were robustly expressed in bladder cancer, and also that the suppression of the METTL3-m6A-CDCP1 axis could restrict the bladder cancer growth and tumorigenesis both in vitro and in vivo." (PMID 33882457, 2021). "For instance, in bladder cancer, the upregulation of METTL3 enhances the methylation of CDCP1 mRNA, promoting its translation and tumor progression." (PMID 40003919, 2025). "In bladder cancer (BLCA), the increase in the expression level of METL3 can upregulate m6A levels of the CDCP1 gene, which promotes the proliferation, migration, and invasion of BLCA." (PMID 38024481, 2022). "In bladder cancer, METTL3 elevates the m6A level of CDCP1, enhancing its translation, which is modulated by YTHDF1, and the upregulation of METTL3 and CDCP1 is correlated with poor prognosis of bladder cancer." (PMID 33758623, 2021). "Yang et al34 showed that METTL3 and ALKBH5 regulated m6A modification of the 3′‐UTR of the oncogene CDCP1 mRNA and that YTHDF1 recognized m6A modification to promote CDCP1 translation in bladder cancer." (PMID 32808488, 2020). "For example, in bladder cancer tumorigenesis, m6A methyltransferase METTL3 and demethylases ALKBH5 mediate the m6A modification in 3’-UTR of CDCP1 mRNA." (PMID 33099572, 2020).
bladder cancer (continued). "Analysis of METTL3 and CDCP1 expression in primary patient samples revealed that METTL3 and CDCP1 are strongly upregulated in the bladder cancer patient samples." (PMID 30796352, 2019). "We further showed that METTL3 and CDCP1 are upregulated in the bladder cancer patient samples and the expression of METTL3 and CDCP1 is correlated with the progression status of the bladder cancers." (PMID 30796352, 2019). "Most importantly, the expression of METTL3 and CDCP1 is correlated with the progression status of the bladder cancers, further supporting the role of METTL3-mediated m6A pathway in bladder cancer oncogenesis." (PMID 30796352, 2019). "It has been confirmed that CDCP1 was overexpressed in bladder cancer cells, mediated by m6A methyltransferase METTL3, m6A reader YTHDF1 preferentially recognizes m6A residues on CPCP1 3′-UTR and enhances the CDCP1 translation, promotes bladder cancer tumorigenesis in vitro and in vivo." (PMID 36650570, 2023). "Moreover, METTL3 has been highlighted to augment the m6A modification in 3’-untranslated region (3'-UTR) of CUB domain containing protein 1 (CDCP1) mRNA, which is positively correlated with the malignancy status of bladder cancer." (PMID 33882457, 2021). "Overexpression of ALKBH5 in bladder cancer J82 cells and UM-UC-3 cells resulted in decreased CDCP1 protein level without changing its mRNA." (PMID 30796352, 2019). "On the other hand, depletion of METTL3 in the transformed MC-SV-HUC-1 cells and bladder cancer T24 cells resulted in decreased level of CDCP1 protein but not the mRNA." (PMID 30796352, 2019). "Similarly, in bladder cancer, METTL3 deposited m6A on the 3′-UTR of Cdcp1, which has been found to promote migration across several cancer types, resulting in YTHDF1-mediated increases in CDCP1 translation and increased cellular migration." (PMID 35350378, 2022). "Interestingly, CDCP1 protein expression, but not its mRNA, is upregulated in transformed cells and bladder cancer cells." (PMID 30796352, 2019). "Immunohistochemistry (IHC) staining of bladder cancer patient tumor microarray revealed that both METTL3 and CDCP1 are moderately or highly expressed in most of the bladder cancer samples, whereas their expression are weak or not detectable in the majority of the paratumor controls." (PMID 30796352, 2019). "Determination of METTL3 and CDCP1 expression in human cystitis and bladder cancer tissues revealed that METTL3 and CDCP1 expressions are weak or not detectable in majority of the cystitis samples, although the METTL3 and CDCP1 are upregulated in the non-muscle-invasive bladder cancer samples." (PMID 30796352, 2019).